RN7SKP280 (RN7SK pseudogene 280)
Gene: Miscellaneous RNA gene on chromosome 7 (155,181,881 to 155,182,184, forward strand). Ensembl gene ENSG00000201066.
Homologues: Orthologues: chimpanzee 7SK (97% identical). Paralogues in human: RN7SKP255 (74% identical), 7SK (74% identical), RN7SKP269 (74% identical), RN7SKP79 (74% identical), RN7SKP176 (73% identical), RN7SKP47 (73% identical), RN7SKP78 (73% identical), RN7SKP243 (73% identical), RN7SKP245 (73% identical), RN7SKP71 (73% identical), RN7SKP163 (73% identical), RN7SKP180 (73% identical), and 284 more.